OR5P3 (olfactory receptor family 5 subfamily P member 3)
Description:
Odorant receptor (Potential). May be involved in taste perception.
Synonyms: JCG1
Tractability: Antibody: its Gene Ontology location is reachable by antibodies, with high confidence; UniProt places it where antibodies can reach, with medium confidence; UniProt predicts a signal peptide or a membrane-spanning region.
Gene: Protein-coding gene on chromosome 11 (7,824,818 to 7,830,840, reverse strand). Ensembl gene ENSG00000182334.
Subcellular location: Cell membrane
Pathways (Reactome):
Sensory Perception: Expression and translocation of olfactory receptors; Olfactory Signaling Pathway
Gene Ontology:
Molecular function: odorant binding; olfactory receptor activity; G protein-coupled receptor activity
Biological process: sensory perception of smell; detection of chemical stimulus involved in sensory perception of smell; G protein-coupled receptor signaling pathway
Cellular component: plasma membrane; membrane
Genetic constraint (gnomAD): Loss-of-function variants: 0 observed, 0.92 expected, observed/expected ratio (o/e) 0, 90% interval 0 to 1.74. That is too few expected variants to judge how well the gene tolerates losing a copy. Missense variants: 394 observed, 379.76 expected, observed/expected ratio (o/e) 1.04, 90% interval 0.95 to 1.13. Synonymous variants: 168 observed, 142.67 expected, observed/expected ratio (o/e) 1.18, 90% interval 1.04 to 1.34.
Homologues: Orthologues: chimpanzee OR5P3 (99% identical), rabbit OR5P3 (82% identical), guinea pig OR5P3 (81% identical), mouse Or5p80 (77% identical), rat Or5p80 (77% identical), mouse Or5p57 (76% identical). Paralogues in human: OR5P2 (64% identical), OR5AP2 (53% identical), OR8D4 (51% identical), OR5AK3P (50% identical), OR5B12 (50% identical), OR5B21 (50% identical), OR5AK2 (49% identical), OR5AR1 (49% identical), OR5J2 (49% identical), OR8B8 (49% identical), OR8D1 (49% identical), OR5A1 (49% identical), and 84 more.
Diseases named in the same sentence as OR5P3 in open-access papers:
OR5P3 is named in the same sentence as 1 disease in open-access papers, as found by Europe PMC text mining. Sharing a sentence is not in itself a finding about the gene and the disease. The quoted sentences say what the papers report.
breast carcinoma (1 paper, 2024). "In addition, a large number of additional detected genes did not fit into known breast cancer progression mechanisms (e.g. SYNDIG1, OVCH2, OR5P3, etc.)and further studies of these targets may yield new insights into additional mechanisms that support breast cancer progression." (PMID 38523186, 2024).